ZGRF1 (zinc finger GRF-type containing 1)
Description:
5'-3' DNA helicase which is recruited to sites of DNA damage and promotes repair of replication-blocking DNA lesions through stimulation of homologous recombination (HR). Promotes HR by directly stimulating RAD51-mediated strand exchange activity. Not required to load RAD51 at sites of DNA damage but promotes recombinational repair after RAD51 recruitment. Also promotes HR by positively regulating EXO1-mediated DNA end resection of double-strand breaks. Required for recruitment of replication protein RPA2 to DNA damage sites. Promotes the initiation of the G2/M checkpoint but not its maintenance. Catalyzes Holliday junction branch migration and dissociation of D-loops and DNA flaps.
Synonyms: C4orf21; FLJ11331
Tractability: PROTAC: ubiquitination databases record sites on it.
Gene: Protein-coding gene on chromosome 4 (112,539,333 to 112,637,392, reverse strand). Ensembl gene ENSG00000138658.
Subcellular location: Nucleus
Subcellular location (Human Protein Atlas): Nucleoplasm
Gene Ontology:
Molecular function: 5'-3' DNA helicase activity; ATP hydrolysis activity; protein binding; helicase activity; zinc ion binding
Biological process: recombinational repair; double-strand break repair
Cellular component: nucleus; site of double-strand break
Genetic constraint (gnomAD): Loss-of-function variants: 146 observed, 151.53 expected, observed/expected ratio (o/e) 0.96, 90% interval 0.84 to 1.11. The upper end of that interval is the gene's LOEUF score, 1.11, which puts it in group 4 of 6, group 1 being the genes least tolerant of losing a copy. Missense variants: 1,913 observed, 2,047.7 expected, observed/expected ratio (o/e) 0.93, 90% interval 0.9 to 0.97. Synonymous variants: 686 observed, 724.5 expected, observed/expected ratio (o/e) 0.95, 90% interval 0.89 to 1.01.
Homologues: Orthologues: chimpanzee ZGRF1 (99% identical), macaque ZGRF1 (94% identical), dog ZGRF1 (78% identical), rabbit ZGRF1 (74% identical), pig ZGRF1 (73% identical).
Diseases named in the same sentence as ZGRF1 in open-access papers:
ZGRF1 is named in the same sentence as 8 diseases in open-access papers, as found by Europe PMC text mining. Sharing a sentence is not in itself a finding about the gene and the disease. The quoted sentences say what the papers report.
Obesity (2 papers, 2015 to 2021). Accumulation of substantial excess body fat. "Interestingly, previous studies have identified ALPK1 (rs4833407), 100kb proximal to ZGRF1, to be associated with obesity in European populations." (PMID 26599207, 2015). "For instance, a significant positive association between log (root−to−tip ω) and log (body mass) was tested in BRAP, STX16, ZGRF1 and ZPLD1, and all four genes were reported to cause obesity in humans." (PMID 34107880, 2021). "Examination of this region in the GIANT (Genetic Investigation of Anthropometric Traits) Consortium for BMI and class 1 obesity (BMI>30) failed to reveal significant signals of association at the ZGRF1 locus (P>0.01)." (PMID 26599207, 2015). "In particular, three obesity-related BSAGs (ST3GAL2, ZGRF1 and ZPLD1) were determined to have undergone rapid evolution in extremely large carnivores, although this was not significant in any of the three after FDR correction." (PMID 34107880, 2021).
apraxia of speech (1 paper, 2024). "Two ZGRF1 variants detected as compound heterozygotes in 7 ASD patients in this study, rs61745597 and rs76187047, have been identified as the potential genetic causality of childhood apraxia of speech (CAS), which is prevalent in approximately 25–30% of children with ASD41." (PMID 38287090, 2024).
cancer (2 papers, 2021 to 2023). A tumor composed of atypical neoplastic, often pleomorphic cells that invade other tissues. "ZGRF1 deletion cancer cells sensitivities to CPT, PARPi and irradiation.It indicates the potential of ZGRF1 to be a promising prognostic and efficient medication guidance biomarker for cancer therapy." (PMID 34552057, 2021). "The colony formation assay of HeLa cells and MD231 cells confirmed that ZGRF1 deletion cancer cells were extremely sensitive to IR induced DNA damage." (PMID 34552057, 2021). "Taken together, our data indicates ZGRF1 is a new potential target for cancer therapy of both DNA damage drugs and irradiation." (PMID 34552057, 2021). "We also provide a new sight for the DNA damage-inducing drugs in cancer therapies in targeting ZGRF1 or ZGRF1-dependent processes." (PMID 34552057, 2021). "Interestingly, most of these genes are linked with cancer processes (Pld1, Fam13c, Svbp, TMem192, Zc3h7a, RTP4, Naa30, Zgrf1, Slc33a1, Dnmt3b, Map6, Plin4, Eps8L2, Alg12, Capg and Tdp2)." (PMID 37700325, 2023). "The cancer cells with deleted ZGRF1, which impairs HR repair, may also be sensitive to PARP inhibitor." (PMID 34552057, 2021). "ZGRF1 is a potential target of radiation and PARPi cancer therapy." (PMID 34552057, 2021). "Our bioinformation analysis data shows that ZGRF1 expression also positively correlates with the mRNA levels of BRCA1 and EXO1, which are well known for PARPi targets, and higher expression of ZGRF1 predicts poor prognosis of patients in several types of cancer." (PMID 34552057, 2021). "Furthermore, higher expression levels of ZGRF1 predicts poor prognosis in cancer therapy, and ZGRF1 knock-out cancer cells are highly sensitivity to DNA damage stress and PARPi." (PMID 34552057, 2021). "We next assessed whether ZGRF1 expression levels are correlated with the development of patients with cancers." (PMID 34552057, 2021). "Given ZGRF1 impaired DNA damage repair by disrupting the DNA end resection, and therefore delayed the G2/M DNA damage arrestment.We consider whether ZGRF1 deletion can promote apoptosis of cancer cells after irradiation." (PMID 34552057, 2021). "Kaplan–Meier analysis revealed that lower ZGRF1 levels in tumor tissues were significantly correlated with increased overall survival (OS) rates in LUAD, PRAD, and the BRAF-like type of THCA cancers." (PMID 34552057, 2021).
tumor (2 papers, 2016 to 2021). "Using allelic retention status in the HCC tumor as a criterion, three genes (UNC5C, DKK2, and ZGRF1) from the LOH region were evaluated for further investigation." (PMID 27203079, 2016).
infection (1 paper, 2025). The state of being infected such as from the introduction of a foreign agent such as serum, vaccine, antigenic substance or organism. "Moreover, genes such as Cpz, Prc1, and Zgrf1, as well as metabolites like oleoyl-L-carnitine, 5-hydroxyindoleacetic acid, and CMPF, were underweighted in the DIABLO analyses but are associated with the infection process, highlighting their potential as biomarkers." (PMID 40475788, 2025).
ZGRF1 also shares sentences with these, for which no sentence is quoted: lung adenocarcinoma (1 paper); neurological disorders (1); prostate adenocarcinoma (1).